NOS3 (nitric oxide synthase 3)
Diseases named in the same sentence as NOS3 in open-access papers (continued):
Sharing a sentence is not in itself a finding about the gene and the disease.
cancer (continued). "Consequently, genetic variants in the NOS3 gene and other ED-related genes may further influence an individual’s susceptibility to VTE, and can potentially influence cancer patient outcomes and treatment success." (PMID 41528397, 2026). "However, the expression pattern of NOS3 and its diagnostic and prognostic potential has not been investigated in a pan-cancer perspective." (PMID 33747912, 2021). "NOS3 was positively correlated and INSR was negatively correlated with the resistance of cancer to the majority of anti-cancer drugs." (PMID 35513851, 2022). "Increased expression of NOS3 influenced occurrence and development of STAD through several canonical cancer-related pathways." (PMID 33747912, 2021). "Further, we observed that LIUS has the tendency to induce antioxidant effects in non-cancer cells by attenuating the gene expression of NOS2 and NOS3, which promote ROS generation, while promoting the expression of antioxidant genes GPX3 and GPX7." (PMID 31355136, 2019). "NOS2 generates higher levels of NO, and appears to be a better cancer biomarker than the other NOS isoforms, NOS1 and/or NOS3, which are both constitutively regulated and generate low NO flux." (PMID 22957045, 2012). "With increasing cancer grade (Gleason 6-10), the expression of CSF1 and NOS3 increased." (PMID 36209194, 2022). "The differential analysis results showed that expression of NOS3 in cancer tissues is 1.765-fold higher than that of corresponding normal tissues (p < 0.0001)." (PMID 33747912, 2021). "Increased expression of NOS3 might influence occurrence and development of STAD through several canonical cancer-related pathways." (PMID 33747912, 2021).
infection (17 papers, 2017 to 2025). The state of being infected such as from the introduction of a foreign agent such as serum, vaccine, antigenic substance or organism. "Beyond CXCL5, our machine-learning approach highlighted several other novel candidates: PDGF-B, Galectin-1, CXCL11, ANGPT1, EGF, TIE2, MCP-2, and NOS3 that each outperformed CXCL5 in discriminating a dormant infection from uninfected joint replacements." (PMID 41387890, 2025). "During an infection, endothelial NO (eNO) is produced in far-lower quantities than inducible NO (iNO), with the role of NOS3 appearing to be more regulatory." (PMID 37630611, 2023). "Western blot analysis showed increased expression of CD31 and VEGF-A in hearts upon infection while that of NOS3 and Arg-I remained unchanged." (PMID 29312293, 2017). "A nine-analyte synovial panel consisting of PDGF-B, CXCL5, CXCL11, MCP-2 (CCL8), ANGPT1, TIE2, EGF, NOS3, and Gal-1 distinguished dormant infection from truly aseptic cases with 100% specificity and positive predictive value (sensitivity 22%, negative predictive value 74%)." (PMID 41387890, 2025). "One re-implantation originally labeled indeterminate by clustering was reevaluated against the nine-marker panel and expressed eight of nine dormant-infection proteins (89%, PDGF-B, Gal-1, CXCL11, ANGPT1, EGF, TIE2, MCP-2, and NOS3) prompting its reassignment as a dormant infection." (PMID 41387890, 2025). "Given the fact that human airway epithelial cells can only express NOS3, we suspect that the correlation observed in our study was driven by a reduced production of eNO that can affect the regulation of innate immune cells during infection." (PMID 37630611, 2023). "NO is produced from L-arginine by three NO synthases (NOS1, NOS2 and NOS3) and NOS2 is responsible for high level of NO production under pathophysiological conditions such as an infection." (PMID 32459575, 2020). "NOS1 and NOS3 are constitutively expressed, and produce small quantity of NO, while NOS2 generates NO for extended periods of time, at high concentrations, being key as regulator and effector during inflammation and infection." (PMID 38841361, 2024). "We observed significantly increased expression of NOS2, but not NOS1 or NOS3, in response to 12 h of SH0165 infection." (PMID 31766159, 2019).
metabolic disease (10 papers, 2009 to 2026). A congenital disorder (due to inherited enzyme abnormality) or acquired (due to failure of a metabolically important organ) disorder resulting from an abnormal metabolic process. "The NOS3 rs2070744 CC genotype was more prevalent among patients with a CVD and/or metabolic disease history (CC vs. CT vs. TT; χ2, p = 0.049)." (PMID 39768338, 2024). "DXT-M achieved this by modulating a network of metabolites (including citrate, taurine, glutamate, alanine, and others), which interact with targets of hepatic drug-metabolising enzymes, NOS3, and LDHA, thereby correcting endogenous metabolic disorders through intrinsic target molecules." (PMID 41155650, 2025).
vascular disorder (6 papers, 2016 to 2023). A general term used to describe any disease affecting blood vessels]. "Among the identified genes in this study, several genes including MTHFR, NOS3, SLC44A2, and NOTCH2 are associated with prothrombotic risk factors and various vascular disorders." (PMID 32038468, 2019).
bacterial infection (3 papers, 2011 to 2023). "A positive correlation between the incidence of bacterial infection, and the gain of a mutant allele, was observed for the polymorphisms rs1799983 (NOS3) and rs1801274 (FCGR2A)." (PMID 37630611, 2023). "A positive correlation was detected between bacterial infections and the NOS3 rs1799983 G allele and the FCGR2A rs1801274 G allele." (PMID 37630611, 2023). "The NOS3 (rs1799983) G allele and the FCGR2A (rs1801274) G allele were positively correlated with the occurrence of bacterial infections in patients; β = 1.96, OR = 7.12, p value = 0.0212; and β = 1.68, OR = 5.4, p value= 0.014, respectively." (PMID 37630611, 2023).
heart disease (3 papers, 2018 to 2025). "While no statistical significance was found, this analysis revealed a trend in the association among air pollution death rates, NOS3 894 polymorphisms and heart disease." (PMID 30071659, 2018).
inflammation (3 papers, 2008 to 2025). Aberrant reaction of the microcirculation characterized by movement of fluid and leukocytes from the blood into extravascular tissues. "Following development of airway inflammation, several strains of mice (MKK3-/-, NOS-2-/-, and NOS-3-/-) had no measurable changes in ECO, in contrast to many others." (PMID 18505586, 2008).
neurodevelopmental disorder (3 papers, 2019 to 2025). A behavioral and cognitive disorder with onset during the developmental period that involves impaired or aberrant development of intellectual, motor, or social functions. "Recent studies also showed that Nos3 and Pik3cd play an important role in neurodevelopmental disorders." (PMID 31582589, 2019).
neurological diseases (3 papers, 2020 to 2023). "The possible role of NOS3 variants on the risk for neurological diseases has been the matter of several recent reports." (PMID 33732155, 2021).
gastrointestinal disorders (1 paper, 2021). "Variables: UGIB (outcome), genetic variants in PTGS1 and NOS3 genes (independent), and sex, age, schooling, ethnicity, previous history of gastrointestinal disorders, Helicobacter pylori serology, comorbidity, drug therapy, and lifestyle (confounding)." (PMID 34290607, 2021).
hematological disease (1 paper, 2022). "In addition, genes associated with hematological disease (e.g., PDE7A, LMAN1, F13A1, OLR1) and mitochondrial biogenesis and redox (e.g., NOS3, ALDH5A1, PRXL2A, SLC25A13, CPT2) were also significantly altered in BPD patients." (PMID 35484630, 2022).
peripheral neuropathy (1 paper, 2021). A disorder affecting the peripheral nervous system. "Moreover, as NOS3 contributes to systemic vasodilation to increase blood supply, a polymorphism such as associated with the current SNPs affect the function of the NOS3 gene that can further worsen the peripheral neuropathy." (PMID 35069435, 2021).
NOS3 also shares sentences with these, for which no sentence is quoted: essential hypertension (14 papers); acute myocardial infarction (7); primary open-angle glaucoma (6); atrial fibrillation (5); carotid atherosclerosis (5); Cirrhosis (4); coronary atherosclerosis (4); hyperhomocysteinemia (4); left ventricular hypertrophy (4); non-small cell lung carcinoma (4); subarachnoid hemorrhage (4); ulcer (4); acute kidney injury (3); congestive heart failure (3); coronary artery spasm (3); hypertriglyceridemia (3); hyperuricemia (3); infarction (3); neuroblastoma (3); neurodegenerative disease (3); osteoporosis (3); Parkinson disease (3); portal hypertension (3); renal dysfunction (3); retinopathy of prematurity (3); Sleep apnea (3); varicocele (3); vitamin D deficiency (3); acute coronary syndrome (2); acute liver failure (2).
A further 182 diseases each share a sentence with NOS3 in 2 papers or fewer.